CXCR2 (C-X-C motif chemokine receptor 2)
Diseases named in the same sentence as CXCR2 in open-access papers (continued):
Sharing a sentence is not in itself a finding about the gene and the disease.
breast cancer (continued). "On the other hand, genetic deletion of CXCR2 in the PyMT (polyoma middle T oncogene) model of breast cancer resulted in increased infiltration of TANs and promotion of tumor growth." (PMID 35158948, 2022). "It has also been used as a molecular marker for targeted therapies, such as chemokine receptor 7 (CXCR7) in BC, CXCR2 in breast cancer, and CXCR5 in prostate cancer." (PMID 36297654, 2022). "Combined with RNA-seq analysis, we found that CXCL1-3 and CXCL8 are highly expressed in co-cultured breast cancer cells, and CXCR2 is the critical receptor to activate the ERK1/2 signaling pathway in CAAs." (PMID 35280694, 2022). "Compared with normal breast tissue, significantly elevated mRNA levels of CXCR2 and LIF in breast cancer-associated adipocytes, and the expression of CXCL1-3, and CXCL8 in breast cancer tissue were up-regulated." (PMID 35280694, 2022). "In our study, the analysis of the CXCR2 expression profile in breast cancer patient tissue biopsies showed that CXCR2 expression is significantly upregulated in patients of the TNBC subtype and other BC subtypes." (PMID 35517812, 2022). "One such example is the CXCR2-dependent recruitment of neutrophilic myeloid derived suppressor cells to cancers such as pancreatic ductal adenocarcinoma, breast cancer or lung cancer." (PMID 35584137, 2022). "Several previous studies have shown that CXCL8 which is a secreted protein functions with its receptors, CXCR1 and CXCR2, to promote the progression of some cancers, such as breast cancer, prostate cancer, lung cancer, and CRC." (PMID 35300114, 2022). "Doxorubicin is a chemotherapeutic agent commonly used in patients with breast cancer and was used in the current study to better understand the effect of CXCR2 inhibition." (PMID 35517812, 2022). "Inhibition of CXCR2 in breast carcinoma models reduced the recruitment of neutrophils into the tumor mass and increased the efficacy of chemotherapy." (PMID 35158948, 2022). "Recently, the CXCL5/CXCR2 axis is sufficient to promote breast cancer colonization during bone metastasis." (PMID 33869023, 2021). "Consistently, systemic CXCR2 KO mice decreased PCNA and F4/80 tumor associated Mφ in mammary tumors." (PMID 34638514, 2021). "CXCR2 KO mice also had a reduced tumor volume after the injection with breast cancer cells, supporting the attenuated tumor burdens in adipocyte-specific CXCR2 cKO mice." (PMID 34638514, 2021). "Of note, IL-8 was shown to promote the proliferation of dormant breast cancer cells in liver through IL-8Rb/CXCR2." (PMID 33771156, 2021). "Blocking CXCR1 and CXCR2 in mice with breast cancer with reparixin, a specific small-molecule inhibitor of CXCR1 and CXCR2, results in decreased levels of NETs." (PMID 34758877, 2021). "CXCR2-targeted therapy has shown previously promising results in several solid tumors, including breast cancer, pancreatic cancer, and rhabdomyosarcoma." (PMID 34012923, 2021). "Meanwhile, more than 90% of naive CD4+ T cells sorted from the mammary tumors exhibited CXCR2 (CXCL1 receptor) expression, which was relatively higher than that in non-naive CD4+ T cells." (PMID 34461944, 2021). "C-X-C motif chemokine receptor-2 has been found to promote anti-apoptosis, anti-senescence, and epithelial-to-mesenchymal transition of breast cancer cells, leading to enhanced metastasis and chemoresistance." (PMID 34456862, 2021). "Several other studies identified CXCR2 as a key player in establishing the metastatic niche of breast cancer." (PMID 34944914, 2021). "CXCR2 gene expression has been described in T cells from older mice (18–22 months of age) and mammary tumor bearing mice, while we used young (aged 8–12 weeks) and healthy mice." (PMID 34029331, 2021). "As neutrophils are also increasingly recognized as key modulators of tumor progression and highly express the chemokine receptor Cxcr2, we decided to evaluate the effect of knocking-down its expression in the murine breast cancer model PyMT." (PMID 34070438, 2021).
breast cancer (continued). "The chemokine receptor CXCR2 promoted breast cancer cell migration, invasion, and metastasis by suppressing Akt1." (PMID 34298660, 2021). "We show here that several ligands of the chemokine receptor Cxcr2 were up-regulated in the PyMT (polyoma middle T oncogene) model of breast cancer." (PMID 34070438, 2021). "In other types of models, Cxcr2−/− mice have been injected with lung cancer cells, breast cancer cells, pancreatic cancer cells, or renal cancer cells, and the authors have observed that deletion of Cxcr2 was reducing tumor growth." (PMID 34070438, 2021). "CXCR2 modulates the trafficking of neutrophils from the bone marrow to breast cancer sites, leading to increased tumor growth." (PMID 33747948, 2021). "Bone is one of the most common sites of breast cancer metastasis, and in studies using ex vivo cultures of mouse long bones co-cultured with PyMT tumor cells, CXCR2 drove tumor cell colonization in the bone explants." (PMID 34944914, 2021). "Ly6GmiLy6Clo CD11b+ CXCR2+ subpopulation (CXCR2+ MDSCs) predominantly proliferates and is recruited in the tumor microenvironment during breast cancer progression." (PMID 34504800, 2021). "This translational approach seems to be particularly promising since first clinical trials employing inhibitors of the aging-promoting chemokine receptor CXCR2 on neutrophils reported positive results in patients with breast cancer." (PMID 34876407, 2021). "An ex vivo tumor/bone co-culture model was used to demonstrate that the CXCL5/CXCR2 axis is sufficient to promote breast cancer colonization during bone metastasis." (PMID 34831167, 2021). "In a murine model of breast cancer metastasis, lungs from tumor-bearing, myeloid-specific CXCR2 KO mice had a decreased M2 macrophage population and an increased CD8+ T-cell population as compared to WT controls." (PMID 34944914, 2021). "Up-regulation of CXCR2 has been found in various cancers, such as ovarian carcinoma, pancreatic carcinoma and breast cancer." (PMID 33814009, 2021). "Overexpression of Akt1 in MDA-MB-231 cells was shown to counteract the effects of the chemokine receptor CXCR2 on breast cancer cell growth, metastasis and chemoresistance by inducing senescence." (PMID 34298660, 2021). "Breast cancer cell lines treated with the CXCR2 antagonist exhibited an increase in CXCL2 as a resistance mechanism." (PMID 34944914, 2021). "The CXCR2-binding chemokines CXCL1 and CXCL8, as well as CXCR2 itself, have also been a focus for drug development and show promise for the treatment of melanoma, breast cancer, ovarian cancer, and pancreatic cancer in preclinical models." (PMID 34200702, 2021). "In breast cancer, CXCR2 inhibitors were demonstrated to be safe and tolerable, and relevant clinical trials are currently underway (NCT02370238)." (PMID 34439836, 2021). "We first compared levels of CXCR2, CD11b and CD66b expression in normal breast tissues from 21 patients undergoing plastic surgery to our cohort of 105 breast cancer patients." (PMID 32727083, 2020). "It would be interesting in the future to determine the prognostic value of CXCR2 for each subgroup of breast cancer patients." (PMID 32727083, 2020). "CXCR2, the receptor for CXCL1, provides one such therapeutic strategy with CXCR2 inhibitors such as Repertaxin currently in Phase II clinical trials in breast cancer." (PMID 33256011, 2020). "In our previous studies, we demonstrated the upregulation of CXCR2 and its ligands after chemotherapy treatment in breast cancer cell lines." (PMID 33049964, 2020). "Here, we targeted CXCR2 for intervention in mice with mammary tumors, disrupting signals from its cognate ligands, CXCL1 and CXCL3." (PMID 33123173, 2020). "The goal of this study was now to determine the expression and prognosis value of CXCR2 in breast cancer, which has been poorly studied." (PMID 32727083, 2020). "Here, we have analyzed the potential role of CXCR2 in breast cancer in a retrospective cohort of 105 breast cancer patients." (PMID 32727083, 2020).
breast cancer (continued). "Pathogenic polymorphisms of other inflammatory genes like NRF2, IL1α, IL1β, IL6, IL8, and CXCR2 have also been identified in Tunisian and Egyptian breast cancer patients." (PMID 33659210, 2020). "It is interesting to mention that the prognosis value of CXCR2 has remained so far poorly studied in breast cancer, whereas it has been analyzed more thoroughly in other cancers." (PMID 32727083, 2020). "We analyzed by IHC CXCR2, CD11b and CD66b expression on a cohort of 105 paraffin-embedded tumors of breast cancer patients that we had previously characterized." (PMID 32727083, 2020). "We next compared the expression of CXCR2, CD11b and CD66b between normal breast tissue and breast cancers." (PMID 32727083, 2020). "In line with this, it was shown on neutrophils isolated from the blood of patients that the percentage of CXCR2 positive neutrophils was lower in breast cancer patients compared to healthy patients." (PMID 32727083, 2020). "We report that obesity increases CXCL1 concentrations in the mammary tumor microenvironment, driving CXCR2-mediated chemotaxis and accumulation of granulocytic myeloid-derived suppressor cells (G-MDSCs) expressing Fas ligand (FasL)." (PMID 33123173, 2020). "We observed that CXCR2 expression was significantly higher in breast cancer tissues compared to the normal one (p = 0.026), whereas CD11b expression was lower in cancer samples (p = 0.001) and CD66b similar in normal and cancer tissues." (PMID 32727083, 2020). "The pattern of CXCR2 expression in breast cancer remains a controversial question, presumably due to the use of a variety of Ab, with distinct specificities." (PMID 32727083, 2020). "When looking in more details to breast cancer tissues, we show that CXCR2, CD11b and CD66b high levels were correlated to a high tumor grade and to TNBC tumors." (PMID 32727083, 2020). "To date, key roles were identified in breast cancer for CXCR1/CXCR2 and their CXCL1/CXCL8 ligands in promoting resistance to chemotherapeutic drugs such as doxorubicin and paclitaxel." (PMID 32582148, 2020). "Another study demonstrated that TNFα activates mesenchymal stromal cells that leads to metastasis in breast cancer through the recruitment of CXCR2+ neutrophils." (PMID 32986377, 2020). "Evidence have shown that CXCR4 drives the metastatic phenotype in breast cancer through induction of CXCR2 and activation of MEK and PI3K pathways, while MMP3 contributes to the precision of epithelial cell branching via the processing of ECM components." (PMID 31798768, 2019). "As mesenchymal cells lead to the formation of various cells of the bone microenvironment, we wanted to evaluate how host CXCR2 affects mammary tumor cells growth in the bone microenvironment." (PMID 30871004, 2019). "We observed that knockdown of CXCR2 in Cl66 mammary tumor cells decreased the ability of tumor cell to grow on calvaria bone and hence resulted in reduced tumor burden." (PMID 30871004, 2019). "In contrast, the contribution of the CXCL5/CXCR2 axis to breast cancer colonization in bone is unexplored." (PMID 31562303, 2019). "Previous reports from our laboratory suggest the role of tumor-derived CXCR2 in mammary tumor growth and lung metastasis." (PMID 30871004, 2019). "In breast cancer, CXCR2+ MDSCs have been shown to promote cancer progression by inducing the epithelial–mesenchymal transition and activated T cell exhaustion." (PMID 31390756, 2019). "This study is an extension of the previous studies and implicates that CXCR2 signaling is also crucial for bone metastasis of mammary tumor cells." (PMID 30871004, 2019). "The present report demonstrates the role of CXCR2 in the process of breast cancer metastasizing to the bone." (PMID 30871004, 2019). "Taken together, our studies implicate targeting CXCR2 as a novel approach for breast cancer treatment." (PMID 30871004, 2019). "Second, we wanted to evaluate how the tumor CXCR2 affects bone damage during breast cancer bone metastasis." (PMID 30871004, 2019).
breast cancer (continued). "This study evaluates the role of CXCR2 in breast cancer bone metastasis by analyzing both tumor-derived and host-derived CXCR2 in the bone microenvironment." (PMID 30871004, 2019). "Additional studies using CXCL5 recombinant protein suggest that CXCL5 is sufficient to promote breast cancer cell proliferation and colonization in bone, while inhibition of its receptor CXCR2 with an antagonist blocks proliferation of metastatic cancer cells." (PMID 31562303, 2019). "With this aim, we implanted breast cancer Cl66-Control and -CXCR2 knockdown cells on the dorsal calvaria of mice and first evaluated the tumor growth." (PMID 30871004, 2019). "Taken together, these studies provide direct evidence of tumor and host-derived CXCR2 in breast cancer progression and metastasis." (PMID 30871004, 2019). "In the present study, we examined the role of both tumor cell-derived and host-derived CXCR2 in influencing mammary tumor cell bone metastasis." (PMID 30871004, 2019). "We also reported that targeting CXCR2 makes tumor cells sensitive towards chemotherapy, again suggesting the importance of CXCR2 signaling in controlling mammary tumor growth and metastasis." (PMID 30871004, 2019). "In our study, we showed that the chemokine/CXCR2 axis is another key upstream activator to trigger SAA1 expression in breast cancer." (PMID 31390756, 2019). "This mini review focuses on preclinical and clinical results obtained by interfering with chemokine receptors CXCR1 and CXCR2 in breast cancer." (PMID 30788286, 2019). "Both MDA-MB-231 and LC breast cancer cells expressed CXCR2, and the CXCR2 levels were higher in LC cells." (PMID 31390756, 2019). "CXCR2 antagonism also inhibits metastasis of breast cancer, lung, ovarian, melanoma cells in mouse models." (PMID 30873179, 2019). "In the present study, we examined the role of both tumor-derived and host-derived CXCR2 in breast cancer bone metastasis." (PMID 30871004, 2019). "Our data suggest the importance of both tumor cell- and host-derived CXCR2 signaling in the bone metastasis of breast cancer cells." (PMID 30871004, 2019). "We then demonstrated that pharmaceutical inhibition of KC binding with reparixin, a CXCR2 antagonist that has been used in trials for the treatment of breast cancer, ameliorated PM-induced increased severity of pulmonary fibrosis." (PMID 31905700, 2019). "Mip-2α was also shown to induce proliferation of tumor cells in a CXCR2-dependent manner in breast cancer." (PMID 30298062, 2018). "CXCR2 inhibition in a preclinical metastatic breast cancer model enhanced response of both tumor and micrometastases to chemotherapy treatment." (PMID 30304046, 2018). "Targeting CXCR2 enhances the antitumor activity of paclitaxel and inhibits mammary tumor growth, angiogenesis, and lung metastasis." (PMID 30034618, 2018). "Targeting IL-8 or its receptors CXCR1/CXCR2 has been shown to suppress tumor growth and induce cancer cell apoptosis in colon and breast cancer mouse models." (PMID 28881741, 2017). "After co-culture with CXCR2+ MDSCs system, breast cancer cells exhibited mesenchymal-like morphology, the expression of ZEB1, Snail and N-cadherin was up-regulated, and ZO1 was down-regulated." (PMID 29383101, 2017). "Therapeutic targeting of the CXCL1/CXCR2 circuit in an adjuvant setting circumvents chemotherapy resistance in breast cancer patients." (PMID 29262555, 2017). "A combination of chemotherapy and CXCR2 inhibition effectively reduced the development of lung metastases after xenograft injections of human metastatic breast cancer cells into mice compared with either treatment alone." (PMID 28450382, 2017). "Here we identify that Ly6GmiLy6CloCD11b+CXCR2+ subpopulation (named CXCR2+ MDSCs) are predominately expanded and recruited in systemic and local tumor microenvironment during breast cancer progression and metastasis." (PMID 29383101, 2017).
breast cancer (continued). "Recently TNFα-activated mesenchymal stromal cells were shown to promote breast cancer metastasis by recruiting neutrophils in CXCR2 dependent manner." (PMID 29340117, 2017). "The most aggressive breast cancer cell behavior was mediated by MAPK pathway activation following viral proteins interaction with CXCR2." (PMID 29021819, 2017). "Why Ly6G and Ly6C are downregulated in CXCR2+MDSCs during breast cancer progression need to be further investigated." (PMID 29383101, 2017). "In this study, we found that Ly6GmiLy6CloCD11b+ CXCR2+ subsets (named CXCR2+ MDSCs) were predominately expanding and recruiting in systemic and local tumor microenvironment during breast cancer progression." (PMID 29383101, 2017). "Breast cancer cells do express CXCR1 and CXCR2, and increasing evidence indicates that IL-8 plays a critical role in enhancing the invasive and metastatic potential of breast cancer cells." (PMID 29021819, 2017). "Taken together, the phenomena observed above implied that CXCR2+ MDSCs played a key role during breast cancer metastasis to lung or lymph node." (PMID 29383101, 2017). "In summary, here we identified a subpopulation of MDSCs in breast cancer which phenotype is Ly6GmiLy6CloCD11b+CXCR2+ (CXCR2+ MDSCs)." (PMID 29383101, 2017). "The IL-8/CXCR1/CXCR2 signaling axis is critical for the establishment of stem-like properties in breast cancer." (PMID 27531902, 2016). "CXCR2 was reported to play a critical role in a range of cancers, such as colon cancer, oral squamous cell cancer, esophageal cancer and breast cancer." (PMID 26497045, 2015). "We therefore conclude that TFF3 secreted from mammary carcinoma cells stimulated angiogenic behavior of HUVEC through IL-8/CXCR2 signaling." (PMID 26559818, 2015). "CXCR4 drives the metastatic phenotype in breast cancer through induction of CXCR2, and activation of MEK and PI3K pathways." (PMID 24524196, 2014). "Treatment with the cytokine TNF-α increased the expression of CXCR2, CX3CR1, CCR9, and CCR5 in breast cancer MCF-7 cell line and caused a marked increase in the expression of CXCR2 and CCR5." (PMID 24591756, 2014). "To understand further the role of the hPTTG1/CXCR2 axis in breast cancer metastasis, we collected 50 human primary IDCs and 50 matched lymph nodes with metastatic carcinoma." (PMID 22789011, 2012). "Immunohistochemical analysis of human breast tumor samples also confirmed the importance of the hPTTG1/CXCR2 axis in promoting breast cancer metastasis." (PMID 22789011, 2012). "When cells are capable of inducing senescence, CXCR2-dependent senescence can inhibit the proliferation and metastasis of breast cancer cells." (PMID 22789011, 2012). "CXCR2 genotype analysis revealed that carriers of CXCR2 (+1208) TT homozygous genotype are significantly over-represented among breast cancer cases (OR = 2.08; P = 0.01)." (PMID 20540789, 2010). "Concerning IL-8 receptors, it has been observed that CXCR1 expression was extremely low in breast cancer cells, whereas most of the cells investigated showed a higher expression of CXCR2." (PMID 20540789, 2010). "Based on the intertwined and interactive roles that IL-8 and CXCR2 play at the molecular level in the angiogenic pathway, we further hypothesized a priori that the joint effect of genetic variants in these angiogenesis regulators may increase breast cancer risk." (PMID 20540789, 2010). "By considering the expression of IL-8 by breast cancer cells and CXCR2 by large vessel and microvascular endothelial cells, an autocrine effect for IL-8 and the chemokine receptor CXCR2 has been suggested." (PMID 20540789, 2010). "We used the allele-specific polymerase chain reaction to characterize the variation of IL-8 and CXCR2 for 409 unrelated Tunisian patients with breast carcinoma and 301 healthy control subjects." (PMID 20540789, 2010). "The genotype frequency of the CXCR2 (+1208) TT was 0.115 in patients with breast carcinoma and 0.06 in control subjects (OR = 2.89; P = 0.008)." (PMID 20540789, 2010).